NLRP3 (NLR family pyrin domain containing 3)
Diseases named in the same sentence as NLRP3 in open-access papers (continued):
Sharing a sentence is not in itself a finding about the gene and the disease.
asthma (176 papers, 2014 to 2026). "Together, these studies support the idea that the NLRP3 inflammasome-induced pyroptosis pathway can contribute to the increased lung immunopathology induced by RSV infection as well as RSV-associated asthma development." (PMID 41011440, 2025). "The expression of NLRP3 and IL‐1β in sputum has been associated with neutrophilic asthma phenotypes in children, correlating with greater disease severity, poor asthma control, and corticosteroid resistance." (PMID 41318536, 2025). "This gain-of-function variant in NLRP3 leads to constitutive inflammasome activation and is associated with severe, adult-onset asthma." (PMID 41394843, 2025). "The NLRP3 inflammasome is a critical mediator of the innate immune response and has been associated with the development of asthma." (PMID 39834584, 2024). "By comprehensively evaluating the interplay between GLCCI1, the PI3K pathway, and NLRP3 inflammasome activation in macrophages, our study provides further insights into the molecular mechanisms underlying the pathogenesis of asthma." (PMID 39834584, 2024). "Single nucleotide polymorphisms (SNPs) in NLRP3 inflammasome and caspase-1 have been linked to the increase in childhood asthma susceptibility." (PMID 39611173, 2024). "While IL‐1β can be secreted through various inflammasomes activated by various triggers, the most extensively researched and closely associated with asthma is the NLRP3 inflammasome." (PMID 38668995, 2024). "NLRP3, an immune sensor of infection and cellular stress, is associated with the development and exacerbation of asthma." (PMID 37530555, 2023). "Inhalation of house dust mite (HDM), the common allergen causing asthma, can promote NLRP3 inflammasome activation in the lung and specifically induce maturation of caspase-1 and IL-1β in alveolar macrophages." (PMID 38274803, 2023). "This study explored the inhibitory effect of MUC1 on NLRP3 inflammasome-mediated pyroptosis in patients with asthma and revealed that one of the underlying mechanisms is the downregulation of TLR4/MyD88/NF-κB pathway activation." (PMID 37880668, 2023). "Clinical observations show that NLRP3-mediated inflammatory response caused by circulating and pulmonary monocytes is a key driver of the pathogenesis of asthma." (PMID 35619697, 2022). "NLRP3 polymorphisms have been significantly associated with the susceptibility to develop asthma in different cohort studies." (PMID 36189256, 2022). "Recent studies have confirmed that activation of NLRP3 inflammasome was significantly associated with the development of severe/refractory asthma using human and mouse asthma models." (PMID 35500231, 2022). "Another recent study conducted using blood samples from an asthmatic children cohort found that the G, C, and T alleles of rs72553860, rs12137901, and rs4925648 NLRP3 SNPs were also associated with asthma susceptibility." (PMID 36189256, 2022). "Nucleotide-binding oligomerization domain-like receptor containing pyrin domain 3 (NLRP3) is closely associated with asthma." (PMID 36595748, 2022). "The data available indicate the importance of NLRP3 in the allergic response and underlines a potential therapeutic effect of RRx-001 on asthma development." (PMID 36203607, 2022). "Despite all the evidence supporting the NLRP3 implication in asthma the underlying mechanisms of NLRP3 activation are still far from being completely understood." (PMID 36189256, 2022). "The MAVS rs6515831 and NLRP3 rs10925023 polymorphisms were associated with the risk of asthma in children." (PMID 36595748, 2022). "using alum-free OVA and HDM models reported that NLRP3 deficient mice presented a similar phenotype to the WT mice when subjected to the experimental asthma protocols." (PMID 36189256, 2022). "The NLRP3 inflammasome has been implicated in human eosinophilic disorders, as well as eosinophil recruitment and Th2 cytokine production in a mouse model of asthma." (PMID 35273610, 2022).
asthma (continued). "In conclusion, the MAVS rs6515831 and NLRP3 rs10925023 polymorphisms were associated with the risk of asthma in children." (PMID 36595748, 2022). "A recent study linked the NLRP3 inflammasome to allergic diseases, revealing an association between two NLRP3 single nucleotide polymorphisms and increased susceptibility to food-induced anaphylaxis and aspirin-induced asthma development." (PMID 33520088, 2021). "Further research on the NLRP3 inflammasome will contribute to the development of novel diagnostic and therapeutic methods for aspirin-induced asthma." (PMID 33912556, 2021). "Environmental pollutant or allergen-activated NLRP3 inflammasome activation has been associated with exacerbation of asthma." (PMID 34868022, 2021). "It has been documented that excessive generation of ROS observed in the airways of asthma patients causes oxidative stress and chronic inflammatory responses in asthma and ROS are crucial for NLRP3 inflammasome activation in bronchial epithelial cells." (PMID 34868022, 2021). "NLRP3, as an immune sensor of infections and cellular stress, is associated with the development and exacerbation of asthma." (PMID 34413860, 2021). "The stimulation of the NOD-, LRR- and pyrin domain-containing protein 3 (NLRP3) inflammasome and IL-1β synthesis are associated with chronic respiratory diseases such as neutrophil-dominant severe asthma." (PMID 34064821, 2021). "Invading pathogens including viral or bacterial which commonly associated with asthma exacerbation, have been shown to trigger NLRP3 activation." (PMID 32117301, 2020). "In this system, Nlrp3 deficiency increased Th1-dependent responses which exerted significant control of disease in mouse models of asthma and metastatic melanoma." (PMID 27926940, 2016). "The NLRP3 inflammasome is closely associated with asthma, especially severe asthma, and its modulation by the gut microbiome may play a key role in asthma pathogenesis." (PMID 39465678, 2025). "Understanding the NLRP3 structure and activation mechanisms is essential, as dysregulation of this complex has been increasingly implicated in the pathogenesis and heterogeneity of pediatric asthma." (PMID 41318536, 2025). "The findings emphasize an association between elevated NLRP3 levels and poor asthma control." (PMID 41318536, 2025). "Finally, the NLRP3 inflammasome and IL-1β signaling in RV-associated asthma were extensively investigated." (PMID 41011440, 2025). "Variants in the NLRP3 gene are associated with an increased risk of asthma in patients." (PMID 40343297, 2025). "Furthermore, the dysregulated activation of the NLRP3 inflammasome has been associated with the development of inflammatory diseases, including asthma, diabetes, atherosclerosis, and Alzheimer's disease." (PMID 38668995, 2024). "GLCCI1 deficiency promotes asthma inflammation through PI3K-induced NLRP3 inflammasome activation." (PMID 39834584, 2024). "Furthermore, we, and others, have identified severe asthma in obese women as a distinct clinical phenotype that is associated with increased NLRP3 inflammasome responses in the airways." (PMID 38044426, 2023). "Therefore, NLRP3 overactivation by DAMPs can be addressed for part of the higher neutrophilic asthma risk experienced by obese patients, together with deconditioning that led to higher bronchial responsiveness." (PMID 37189844, 2023). "Recent evidence suggests that NLRP3 activation is not only a key component of the innate immune response in airways but that it is also involved in asthma pathogenesis and is associated with asthma exacerbation and severity." (PMID 36677800, 2023). "Serum vitamin D levels is associated with obese asthma, and NLRP3 inflammasome may play a role in this disorder." (PMID 36051916, 2022). "Single nucleotide polymorphisms (SNPs) analysis indicated that the NLRP3 SNPs might play a significant role in the development of aspirin-induced asthma in a gain-of-function manner." (PMID 33912556, 2021).
asthma (continued). "Variants in the Nlrp3 gene increase the risk of asthma in patients." (PMID 34413860, 2021). "Although the NLRP3 inflammasome is essential for providing protective immunity, overactivation of inflammasome-mediated responses can cause excessive inflammation, tissue damage, and lead to chronic inflammatory diseases, including asthma." (PMID 31590215, 2019). "Pharmacological inhibition of NLRP3 or IL-1 signaling is currently under investigation for inflammatory diseases, and our data suggest these strategies could be extended to pollution-associated asthma endotypes." (PMID 41346596, 2025). "However, there have been no reports indicating whether GLCCI1 deficiency in patients with asthma contributes to enhanced airway inflammation through activation of the PI3K pathway or activation of the NLRP3 inflammasome." (PMID 39834584, 2024). "The activation of NLRP3 plays a crucial role in various metabolic conditions however, too much activation of the inflammasome can cause excessive inflammation and damage to tissues, contributing to the development of chronic inflammatory diseases such as asthma." (PMID 37251328, 2023). "Persistent activation of the NLRP3 inflammasome has been implicated in the pathophysiology of a number of inflammatory and autoimmune diseases, including neuroinflammation, cardiovascular disease, non-alcoholic steatohepatitis, lupus nephritis and severe asthma." (PMID 37598239, 2023). "T2-low asthma patients are characterized by sputum neutrophilia secondary to the activation of the NLRP3 inflammasome and elevated IL-1β; the activation of Th1 and/or Th17 cells associated with the imbalance of Th17/Treg cells seems to play an essential role in the pathology of asthma." (PMID 36614301, 2023). "Moreover, in the case of NLRP3, the existence of contrasting findings further pinpoints the need for a deeper understanding of asthma-related NLRP3 and inflammasome-driven mechanism, and at the same time, underlines the complexities of asthma." (PMID 36189256, 2022). "Therapeutic strategies used in other NLRP3-related inflammatory diseases such as juvenile idiopathic arthritis and ulcerative colitis can also be applied to asthma." (PMID 41318536, 2025). "NLRP3 and IL-1β inhibition in mice infected with RV resulted in an asthma-like phenotype, including increased mucus production and type 2 inflammation in immature mice compared to mature mice." (PMID 41011440, 2025). "To analyze the impact of NLRP3 on the development of type 2-driven experimental allergic asthma, we compared NLRP3-/- and WT mice in a well-established murine asthma model." (PMID 41394833, 2025). "Second, they identify the NLRP3 inflammasome as a potential therapeutic target for pollutant-exacerbated asthma." (PMID 41346596, 2025). "In conclusion, these findings identify KIF1B as a key regulator of airway inflammation and pyroptosis in asthma via NLRP3‐dependent signalling." (PMID 41384344, 2025). "People with asthma had more NLRP3, ASC, caspase-1, and the pro-inflammatory cytokines IL-1β and IL-18 in their bronchoalveolar lavage fluid and sputum samples." (PMID 41318536, 2025). "Therapeutic strategies targeting NLRP3 in asthma will need to consider its dual role in both inflammation and epithelial barrier homeostasis." (PMID 41394833, 2025). "Conversely, microRNAs like miR-223-3p, which suppresses NLRP3 translation, are downregulated in severe asthma, permitting inflammasome hyperactivation." (PMID 41394843, 2025). "In germ-free mice, IL-1 induction is absent, while macrophage-stimulated fecal contents from normal mice elicit IL-1 production in vitro, highlighting the role of colonized bacteria in activating the NLRP3 inflammasome and promoting asthma progression." (PMID 39465678, 2025). "In asthma, the NLRP3 inflammasome plays a role in airway inflammation by promoting the release of inflammatory cytokines such as IL-1β." (PMID 40851698, 2025).
asthma (continued). "Activation of NLRP3 has been observed in both innate immune cells and airway structural cells during asthma, but its role in linking environmental pollutants with adaptive immune responses has not been addressed." (PMID 41346596, 2025). "The inflammasome signaling pathway regulates inflammation in asthma, particularly through activation of the NLRP3 inflammasome." (PMID 40598285, 2025). "A recent study involving a pediatric cohort found that NLRP3 polymorphisms (such as rs10925023, rs10754558), along with variants in MAVS and IL-18, were significantly linked to a higher risk of asthma, increased IgE levels, and greater disease severity." (PMID 41318536, 2025). "Collectively, these findings underscore the importance of the NLRP3 inflammasome in asthma pathophysiology and environmentally induced asthma pathogenesis." (PMID 40832584, 2025). "Targeting NLRP3-driven cytokine signaling in specific pediatric asthma is rational because sputum-based studies and translational models have started to clarify the pathway’s function in airway inflammation and remodeling." (PMID 41318536, 2025). "Despite their different initiating triggers, airway allergen exposure in asthma, microbial imbalance and dysbiosis in IBD, or genetic predisposition in JIA, these disorders converge on a common two‐signal model of NLRP3 activation." (PMID 41318536, 2025). "Exposure to inhaled irritants or allergens can trigger the activation of the NLRP3 inflammasome, potentially resulting in the aggravation of asthma symptoms and pulmonary inflammation." (PMID 40299440, 2025). "Further research is needed to decipher the multiple NLRP3-related pathways with the aim of tailoring inflammasome-targeting therapeutic strategies to individual asthma phenotypes." (PMID 41394833, 2025). "Several studies have shown that the NLRP3 inflammasome is involved in the development of chronic airway inflammation in asthma and COPD." (PMID 41394833, 2025). "The role of the NLRP3 inflammasome in asthma is not limited to cytokine production; it also influences macrophage polarization, particularly promoting the M2 phenotype through IL4 upregulation, which contributes to the chronic inflammation observed in asthma." (PMID 40598285, 2025). "This section will explore how the NLRP3 inflammasome functions at the molecular level, linking innate immune sensing to airway inflammation and remodeling relevant to asthma phenotypes and severity." (PMID 41318536, 2025). "Giving NLRP3 inhibitors to animals lowers airway hyperresponsiveness and inflammation, which supports the concept that targeting this pathway in human asthma is helpful." (PMID 41318536, 2025). "In summary, we show that BaP, a representative environmental pollutant, exacerbates allergen-induced asthma through NLRP3-dependent activation of dendritic cells, leading to Th2/Th17 polarization and severe airway inflammation." (PMID 41346596, 2025). "This enhancement of CLOCK translation by YTHDF1 is instrumental in the inflammatory process, as YTHDF1 further activates the NLRP3 inflammasome, leading to the production of IL‐1β, a key cytokine in asthma‐related airway inflammation." (PMID 41473388, 2025). "Obese rats with asthma showed significant increases in airway inflammation, pro‐inflammatory cytokine levels, and NLRP3 and IL‐1b mRNA expression." (PMID 40309648, 2025). "Accumulating clinical evidence has shed light on the role of NLRP3 inflammasome activation in the pathogenesis of asthma." (PMID 40343297, 2025). "The NLRP3 inflammasome also regulates ferroptosis in asthma inflammation through the JAK2/STAT3 pathway." (PMID 41550926, 2025). "In the context of pediatric asthma, this broader perspective underscores the importance of NLRP3 signaling as both a mechanistic contributor to airway inflammation and a potential biomarker of disease severity." (PMID 41318536, 2025).
asthma (continued). "A cross-sectional study by Li and Liu demonstrates the significantly elevated levels of serum NLRP3 in children with asthma in comparison to healthy controls." (PMID 41318536, 2025). "A 2024 cross‐sectional study demonstrated significantly elevated levels of NLRP3, IL‐1β, and IL‐6 in children with asthma compared to healthy controls, with the highest levels observed in those with moderate to severe disease." (PMID 41318536, 2025). "Andrographolide, a bioactive natural compound isolated from Andrographis paniculata, has also been reported to effectively suppress NLRP3 inflammasome activation and ameliorate inflammatory pathologies in conditions such as asthma and rheumatoid arthritis." (PMID 40688353, 2025). "The canonical NLRP3 inflammasome is the predominant driver of pyroptosis in allergen-induced, Th2-high asthma." (PMID 41394843, 2025). "The ability of mefenamic acid to inhibit the NLRP3 inflammasome offers additional therapeutic potential by decreasing the airway inflammation mediated by IL-1β, a key cytokine involved in severe asthma." (PMID 40851698, 2025). "This section explores the detection and measurement of NLRP3 inflammasome components in sputum samples from pediatric asthma patients." (PMID 41318536, 2025). "The mitochondrial signaling pathways involved in asthma include the activation of inflammasomes, such as the NLRP3 inflammasome, which is triggered by mitochondrial ROS and contributes to the inflammatory cascade in the bronchial epithelium." (PMID 40598285, 2025). "Accurate assessment of NLRP3 inflammasome expression in children with asthma hinges on obtaining reliable airway samples." (PMID 41318536, 2025). "The NLRP3 inflammasome has an important role in the pathogenesis of pediatric asthma, especially in neutrophilic corticosteroid-resistant types." (PMID 41318536, 2025). "Growing clinical evidence has highlighted the key role of NOD-like Receptor Family Pyrin Domain Containing 3 (NLRP3) inflammasome activation in the pathogenesis of asthma." (PMID 40343297, 2025). "The evidence discussed thus far demonstrates NLRP3’s role across multiple pediatric inflammatory diseases, including asthma." (PMID 41318536, 2025). "This review article investigates the mechanism of NLRP3 inflammasome activation as well as its role in airway inflammation and its expression in pediatric asthma based on sputum studies." (PMID 41318536, 2025). "A lot of studies, both on animals and on individuals with asthma, show that the NLRP3 inflammasome is a big part of airway inflammation." (PMID 41318536, 2025). "It is worth noting that “severe asthma,” “NLRP3 inflammasome,” “innate lymphoid cells” and “NF-κB” are the hot keywords with high intensity and long duration." (PMID 39029036, 2024). "We then explored the relationship between GLCCI1 and both the PI3K pathway and NLRP3 inflammation in patients with asthma." (PMID 39834584, 2024). "Recent studies have shown that the NLRP3 inflammasome was involved in regulation of the neutrophilic airway inflammation in patients with severe asthma." (PMID 38811424, 2024). "Treatment with miR-223 agomirs in neutrophilic asthmatic mouse models attenuates airway inflammation, reduces NLRP3 levels, and decreases IL-1β release, suggesting miR-223 as a potential therapeutic candidate for severe non-T2 asthma." (PMID 39554494, 2024). "The expression levels of genes encoding GLCCI1, NLRP3 inflammasome components, and PI3K pathway-related indicators were detected in cells isolated from induced sputum from patients with asthma and healthy controls." (PMID 39834584, 2024). "On the one hand, M2 macrophages promote Th2 cell activation in asthma, and on the other hand, NLRP3 is an important transcription factor for Th2 cell differentiation and induces Th2 inflammatory responses in asthmatic mice." (PMID 39108751, 2024).